CD4 (CD4 molecule)
Diseases named in the same sentence as CD4 in open-access papers (continued):
Sharing a sentence is not in itself a finding about the gene and the disease.
tumor (continued). "al. observed that CD8+ tumor-infiltrating lymphocytes together with CD4+ tumor-infiltrating lymphocytes and dendritic cells were associated with improved postoperative survival, whereas the same was not present when CD8+ and CD4+ cells were present alone without the other population." (PMID 36428747, 2022). "However, there is evidence suggests that IL-2 may preferentially expand CD4+ regulatory T (Treg) cells rather than tumor-killing CD8+ cytotoxic T cells (CTLs)." (PMID 35432319, 2022). "The contradictory observations regarding tumor grading and the amount of CD3+ lymphocyte infiltration could be due to the small number (n = 50) of patients included in our study but also to the fact that the CD4+ FoxP3+ lymphocytes are only a subgroup of lymphocytes." (PMID 35326691, 2022). "Pro-inflammatory cytokines produced by TAMs could trigger the accumulation and expansion of CD4+ Th17 cells to foster angiogenesis and overexpressing CTLA-4, programmed death-1 (PD-1), and glucocorticoid-induced tumor necrosis factor receptor (GITR), thereby promoting tumor development." (PMID 36168626, 2022). "Furthermore, the number of PAt conventional CD4 (but no other T cell subset) correlated with a reduction in tumor growth independent of treatment, supporting the therapeutic significance of this Tocky category of effector CD4 cells, even in the non-curative conditions of double therapy." (PMID 35338089, 2022). "However, activated antigen-specific CD4+ T-cell adoptive transfer significantly reduced metastatic foci in the lung, irrespective of endogenous cell depletion, indicating that tumor control is independent of endogenous CD4+ T, CD8+ T, NK cells, and macrophages." (PMID 35784297, 2022). "However, the mechanism of CD4-mediated tumor rejection has not been clearly delineated." (PMID 35903540, 2022). "Moreover, levels of CD4+PD-1+ T cells were correlated with levels of FoxP3+ Tregs, Helios+ T cells, FoxP3+Helios+ Tregs, FoxP3+Helios− Tregs, and FoxP3−Helios+ T cells in normal tissues, indicating that PD-1 expression is not induced solely by tumor cells." (PMID 35455287, 2022). "It has been found that the major histocompatibility complex II (MHC II) UVM vaccine can activate tumor-specific CD8+T cells and CD4+T cells, thereby killing tumor cells but does not affect normal cells, suggesting that the high-risk group receiving the MHC II UVM vaccine may have better efficacy." (PMID 36568076, 2022). "In addition to conventional T cells (CD4 and CD8 T cells), innate-like T cells, including MAIT cells, natural killer T (NKT) cells, and γδT cells, have been shown to play a pivotal role in tumor immunity, raising the possibility of using or targeting these cells in tumor therapy." (PMID 36551916, 2022). "Likewise, in PR_Ai2mut-immunized mice, the immune recognition of aa 74–85 by CD4+ T cells without effector/with Treg activity (or turned into Tregs after infiltration) could have enhanced tumor growth and increased the metastatic activity of PR20.2 cells." (PMID 36612231, 2022). "However, during tumor development at 40 weeks of being on a WD, the ratio of the hepatic CD4+ and CD8+ T cells to MDSC significantly decreased in males, while females only decreased the CD4+ T cells/MDSC ratio, with the CD4+ T cells/MDSC ratio lowering below a 1:1 ratio in males and females." (PMID 35235789, 2022). "Moreover, TGF-β1 promotes survival of post-thymic naïve CD4+ T lymphocytes to later promote CD4+CD25+ Treg differentiation from uncommitted peripheral CD4+ cells via FOXP3 and Smad3, while preventing its differentiation into the Th-1 and Th-2 effector cell, thereby leading to tumor cell tolerance." (PMID 34299192, 2021). "As hTERT is expressed throughout the tumorigenesis, this CD4+ Th1 response may stay activated and relevant regardless of the tumor’s rapidly evolving genetic makeup, providing the immune system with an opportunity to mount an individually tailored immune response to relevant target antigens." (PMID 34290704, 2021).
tumor (continued). "In addition, the positive signals of CD4+ T cells, macrophages (CD68+) and M2 macrophages (CD163+) were located in the microenvironment of the tumor invasion front, while CD8+ T cells were distributed not only in the microenvironment of the tumor invasion front but also within the tumor glands." (PMID 33818637, 2021). "Furthermore, this study suggests that the depletion of CD4 T cells or regulatory T cells might contribute to tumor inhibition rather than development." (PMID 34777255, 2021). "The amplification of genes such as COL5A1, IDO1, and GOLIM4 were in accordance with their higher expression in tumor samples, whereas no significant change of protein or phosphorylation levels was observed for genes with genomic amplification, such as CD4, CD7, LIME1, UNC93B1, C1S, C1R, or C8G." (PMID 34400640, 2021). "However, the behavior of CD4+ cells in tumor tissue has not been investigated." (PMID 34106609, 2021). "After observing the critical role of BATF downstream of IL-21 signaling in tumor-infiltrating effector CD8+ T cell differentiation, infiltration, and function, we wanted to explore whether BATF overexpression in tumor-specific CD8+ T cells could bypass their need for CD4+ T cell help." (PMID 33809259, 2021). "By analyzing the trajectories of T cells in freshly isolated human lung tumors, both CD4+ and CD8+ T cells were shown to be entrapped within fibronectin- and collagen-rich stromal regions and the restricted access to the tumor could be lifted by treating the tumor samples with collagenase." (PMID 33466303, 2021). "Similarly, CD4+ naive T cells (cluster 0) located at the core of the tumor have significantly higher activation levels in angiogenesis, epoxygenase cytochrome P450, NOTCH3 signaling, lipid particle organization and other pathways than those at the edge of the tumor." (PMID 34513820, 2021). "Hence, CD4-positive T cells and CD20-positive B cells possibly act as the “guides” in participating anti-tumor responses indirectly in TS through secreting IFN-γ and recruiting and activating T cells, B cells, and NK cells, while CD8-positive T cells tend to directly kill tumor cells in TN." (PMID 34804034, 2021). "The UN-KC-6141 model used in this study, similar to the CT26 tumor model, could be considered as an “uninflamed” or “cold” tumor with relatively low numbers of CD4+ (~1%) and CD8+ (~2%) T cells and no response to anti-PD-L1 therapy because only 12.5% CD8+ T cells express PD-1." (PMID 33669885, 2021). "Furthermore, preclinical models described that CD4+ CAR T cells persist and keep their effector potency much longer after tumor challenge; they might even outperform CD8+ CAR T cells, especially at high tumor load." (PMID 33546283, 2021). "Moreover, PCSK9 deficiency failed to retard tumor growth in mice depleted of CD8+ T cells, while depletion of CD4+ T cells had hardly any impact, which led CD8+ cytotoxic T cells (CTLs) to be identified as the most critical for the anti-tumor effect of PCSK9 deficiency." (PMID 33677469, 2021). "Although noncontiguous CD4+ T cell epitopes had not previously been described in any disease, since 2004 there have been several reports of noncontiguous epitopes generated by the proteasome and recognized by tumor-reactive cytotoxic CD8+ T cells isolated from cancer patients." (PMID 34044020, 2021). "Memory CD4+ T cells could provide a protective response against cancer cells by making effector cytokines respond early and by enhancing CD8+ T and B cell responses, as well as by secreting cytokines that can induce other cells in the tumor microenvironment to mount antitumor immunity." (PMID 33917869, 2021). "The correlations between the different immune cell types in the tumor microenvironment showed that immune cells may influence each other and have some cross-talking—for example, there is growing evidence for alternative CD8(+) T cell fates influencing CD4(+) T-cell-mediated responses." (PMID 34887858, 2021).
tumor (continued). "The higher percentages of both CD4 and CD8 T cells in spleen and blood suggest that mice treated with NBTXR3 + HDXRT + LDXRT + ICIs maintained a long-term adaptive immune response against tumor, which could be responsible for eradicating the re-injected cancer cells." (PMID 34895262, 2021). "Nevertheless, neither high CD4+ nor CD8+ lymphocytes were significantly associated with improved survival for patients with oral or laryngeal cancer, indicating that tumor location could be a more discriminating factor than TILs in terms of clinical outcome in HNSCC." (PMID 34201050, 2021). "In addition, the infiltration of CD4+CD39+ T cells tended to decrease (normal versus tumor = 14.43% ± 12.67% versus 7.01% ± 8.73%; P = 0.22) and the frequency of CD8+CD39+ T cells (normal versus tumor = 8.60% ± 4.58% versus 12.02% ± 12.92%, P = 0.67) tended to increase in RSCRC." (PMID 34283812, 2021). "Although it should not be concluded from these few cases that CD8+ T cells are dispensable, they suggest that for certain patients, for example when no autologous CD8+ T cell product with tumor reactivity can be derived, CD4+ T cell-based therapy could be helpful." (PMID 33546283, 2021). "We hypothesize that the CD4+ T cells activate CD8+ cells rather than directly killing tumor cells." (PMID 33668827, 2021). "Moreover, the infiltrations of CD11c+ DCs, CD3+CD4+, and CD3+CD8+ T cells in tumors of the ES-DSM + MW + CD39/anti-CRTα group were significantly decreased due to the deactivation of ATP and CRT, demonstrating that the ICD of tumor was critical during the tumor immunotherapy." (PMID 34362890, 2021). "However, following ex vivo stimulation with SIINFEKL peptide IFN-γ, TNF-α nor IL-2 production was increased in combination treated mice spleen but not tumor compartment, suggesting that antigen-specific CD4 T cells reside prevalently in secondary lymphoid organ." (PMID 34276686, 2021). "Thus, upregulation of PD-L1 on CSCs, but not tumor cells, may be responsible for the induction of CD4+ T cell anergy." (PMID 34065396, 2021). "Among CD3+ T cells, 44.3% were CD8+ and 43.5% were CD4+ T cells without co-culturing with target tumor cells, while 63% were CD8+ and 27.9% were CD4+ T cells after co-culturing with SW480, suggesting that CD8+ T cells may play a more important role in specific cytotoxicity." (PMID 34790117, 2021). "Thus, the potency of CR in dampening tumor growth and metastasis could be explained by the inhibition of FoxP3+CD8+ Tregs, which, in turn, results in increased proliferation of antitumor cytotoxic T cells (CD8+ and CD4+)." (PMID 34707136, 2021). "The defect in effector CD4+ T-cell expansion could be restored by B3-Ab:env123–139 immunization of mice bearing established lung metastases, although this alone did not translate to tumor regression or control, and the expanded CD4+ T cells continued to express high levels of PD-1 and LAG3." (PMID 32313208, 2021). "In summary, our results showed that when an AAV carrying the CD4-CAR gene was infused into mice, it could quickly reprogram lymphocytes and generate sufficient CAR cells to induce ATL regression in NCG-HuPBL mice, suggesting that ACG could be a potential strategy for tumor treatment." (PMID 34162832, 2021). "Ectopic expression of the SMAD3 2KQ mutant, but not WT, not only rescued KAT6A KD‐inhibited tumor growth, lung metastasis, markedly reduced the animal survival, but also promoted MDSCs recruitment to lung tissues and primary tumor, CD4+/CD8+ T cells depletion in metastatic lung tissues." (PMID 34392614, 2021).
tumor (continued). "Furthermore, we show that the co-expression of CD8α in CD4+ TEG011 provides additional survival signal and facilitates better T-cell persistence and infiltration in vivo, both of which are essential to sustain long-term tumor control of adoptively transferred TCR-based immunotherapy." (PMID 34759930, 2021). "We cannot entirely exclude that superior tumor control in TEG011_CD8α may have been caused initially by more CD8 single-positive cells in the TEG011_CD8α product compared to TEG011 product, as CD4+/CD8+ ratios could not be entirely controlled in the experimental setup prior to infusion." (PMID 34759930, 2021). "Furthermore, IFN-γ/IL-2 profile of cytokine production (without TNF-α) could be ascribed to regulatory T cells that suppress the anti-tumor functions of CD4 +, CD8 +, and NK cells, leading to an absence of effective anti-tumor immune response." (PMID 34199989, 2021). "It is thought that Treg cells may decrease the proliferation of effector CD4 and CD8 T lymphocytes in the tumour microenvironment by contact inhibition, subsequently reducing the anti-tumour immune response and resulting in the potential for tumour cells to escape immune surveillance." (PMID 33995362, 2021). "Notably, both the magnitude and the means of several CD8+ or CD4+ Teff cell responses against the single NM-neoAg peptide pools were higher in the subset of naive patients showing earlier stage tumor and who did not experience any neo-adjuvant chemotherapy before surgery, as compared with HDs." (PMID 32099064, 2020). "Regarding CD4 cells, our observation is also in agreement with previous data showing the presence of these cells to correlate with longer survival specifically in ER-negative cases, although in this study lymphocytes were quantified throughout the tumour without analyses of separate compartments." (PMID 32577938, 2020). "Consequently, the ratios of CD4+ and CD8+ T cells to MDSCs or TAMs were increased following Doxil® treatment, which is anticipated to contribute, at least in part, to the increased antitumor efficacy of Doxil® in the tumor-bearing mice compared to the free drug." (PMID 33086690, 2020). "Therefore, the correlation between the percentage of CD4+CD25+CD127lowTregs and the concentrations of TGF-β1 and IL-10 in this study will provide some insight for more in-depth studies on the tumorigenetic mechanism, and facilitate the development of more effective tumor treatment programs." (PMID 32218692, 2020). "Recognition of certain TAA autoepitopes by T cells lacking lytic potential, particularly by Tregs and/or Th17 CD4+ T cells, may lead to their infiltration into tumors and mouse organs harboring tumor cells, with subsequent stimulation of tumor growth and metastases formation." (PMID 32570805, 2020). "Moreover, correlation analysis of immunocyte infiltration also revealed that the seven-IRG prognostic model was positively associated with five types of immunocytes (dendritic cell, macrophage, CD4 T cell, CD8 T cell, and neutrophil), which may directly reflect tumor immune state in COAD." (PMID 32788867, 2020). "Interestingly, an oxaliplatin-resistant colorectal cancer cell line was shown to express increased TERT levels; this suggests that the input of another effective cytotoxic drug to manage chemoresistant tumor cells may facilitate anti-TERT immunity and possibly activate novel CD4 T cell clones." (PMID 32630460, 2020). "Additionally, TLR9 engagement increases the number of CD4+ and CD8+ T cells by boosting the expression of IL-2 and of its associated receptor IL-12R, which takes place even in the absence of costimulatory molecules (such as CD28) in a tumor microenvironment." (PMID 32012718, 2020). "In addition, it is not clear yet whether CD4 memory T cells could also play a role within the tumor microenvironment under PD-L1/PD-1 blockade therapy." (PMID 33329566, 2020).
tumor (continued). "Some tumor markers were associated with other tumor characteristics at diagnosis, notably FAS, which was overexpressed in ER+ tumors, PR+ tumors, and tumors of lower grade, COX-2, which was overexpressed in HER2− tumors, and CD4, which was overexpressed in tumors without nodal involvement." (PMID 32698885, 2020). "However, the significant correlation between the expression of E2Fs and the infiltration of the six immune cell types in PAAD: B cells, CD8+ T cells, CD4+ T cells, macrophages, neutrophils, and dendritic cells, suggests that E2Fs may be involved in the regulation of PAAD tumor immunity." (PMID 33604289, 2020). "Moreover, a study investigating tumor microenvironment, demonstrated that the use of low doses of the anti-VEGF receptor 2 (VEGFR2) antibody was able to polarize the immune inhibitory M2-like phenotype towards the immune stimulatory M1-like phenotype and to recruit CD4+ and CD8+ T-cells." (PMID 32992823, 2020). "Previous studies have confirmed that CD4+ T cells, upon differentiation, may acquire various functions, including blocking cytotoxic NK cells and activating CD8+ T cells, suppressing harmful immunological reactions to self- and foreign antigens, and aiding CD8+ T cells in tumor rejection." (PMID 33585439, 2020). "Thus, although immune CD4+ T cells might not act as direct effectors in eliminating the tumor cells, they were absolutely necessary and sufficient for protecting naïve animals from very tumorogenic tumors." (PMID 33138029, 2020). "TILs include CD8+ T-cells, Tregs, regulatory B-cells (Bregs), type II NK T-cells (which recognise lipid antigens and are not the same as NK cells), and Th2 CD4+ cells which upregulate B-cell responses, play roles in remodeling and may or may not promote tumour growth." (PMID 32937961, 2020). "Additionally spaghetti plots of individual mice in each of the treatment groups showed complete regression in 9/10 mice in the CTX + IL-1α-NP treatment group compared to no tumor regression in the CTX + IL-1α-NP + anti-CD4 and CTX + IL-1α-NP + anti-CD8 treatment groups." (PMID 30890189, 2019). "In addition, patient survival may be improved by increasing the numbers of CD3+ and CD8+ cells but not CD4+ cells in tumours." (PMID 31729963, 2019). "Thus, after inoculation with human commensal microbes of responder patients in mice, the tumor microenvironment showed an increase of SIY-specific CD8+ T cells, but not of FoxP3+CD4+ regulatory T cells which lead to an increased priming of tumor antigen–specific CD8+ T cells." (PMID 31067796, 2019). "In addition, a subset of the responding CD4+ T cells expressed forkhead box protein P3 (FoxP3), indicating that although a regulatory component of the vaccine-activated CD4+ T cell response was induced, the anti-tumor vaccine response was not limited by these regulatory CD4+ T cells." (PMID 30956760, 2019). "Finally, H4R-deficient mice show decreased Tregs in spleens and non-draining lymph nodes, and a negative correlation between tumour weight and the percentages of CD4+, CD19+ and NK splenic cells, suggesting that H4R also regulates antitumour immunity at a systemic level." (PMID 29988113, 2019). "Interestingly, lower KMO mRNA expression was seen in CD4+ T-cells upon co-culture with MCLs, suggesting that KMO may play a role in determining the levels of KYNA and may also be an exciting candidate regulating the kynurenine pathway in tumour immunity." (PMID 31434983, 2019). "The results revealed that the CD4+PD-1+ lymphocytes co-cultured with PD-L1 overexpressed K7M2 cells could promote cell proliferation, indicating that the PD-1 combined with PD-L1 in K7M2 cells could lead an immunosuppressive tumor microenvironment and promote the survival of OS." (PMID 31864288, 2019). "Moreover, CD4+ T cells could mediate eradication of MHC II negative tumor cells through indirect recognition of tumor antigen or upon cooperation with NK cells." (PMID 30853959, 2019).